IL1B (interleukin 1 beta)
Diseases named in the same sentence as IL1B in open-access papers (continued):
Sharing a sentence is not in itself a finding about the gene and the disease.
mesothelioma (11 papers, 2013 to 2025). A usually malignant and aggressive neoplasm of the mesothelium which is often associated with exposure to asbestos. "They provided the rationale for chemoprevention approaches targeting IL-1β/IL-1R signaling in populations at high risk of mesothelioma due to asbestos exposure." (PMID 38784478, 2024). "These and other findings from this study linked inflammation-related IL-1β/IL-1R signaling with the development of asbestos-induced mesothelioma." (PMID 38784478, 2024). "This was verified by Vδ2 T/mesothelioma co-culture experiments demonstrating membrane ballooning morphology, increased cleaved caspase-3 and gasdermin E, and upregulated IL-1β and IL-18." (PMID 38077396, 2023). "Their studies revealed that IL-1β induced by TAZ was a key factor for the development of malignant phenotype of mesothelioma cells." (PMID 35865173, 2022). "Our in vitro studies show that mesothelial cells secrete IL-1β in response to asbestos/erionite which can then affect the same population of mesothelial cells in an autocrine manner, thus transforming them to become mesothelioma cells." (PMID 23937860, 2013). "Similarly, the Wnt/IL-1β/IL-8 pathway was shown to induce ABCB5 expression in mesothelioma, and three signaling pathways, NF-κB, α6-β4-integrin, and IL-1, were overexpressed in ABCB5+ melanoma cells purified by immunomagnetic selection and abcam 140667 anti-ABCB5 antibody." (PMID 39267923, 2024). "Interestingly, live-imaging of Vδ2 T cells co-cultured with mesothelioma showed the induction of pyroptosis in the cells, which was confirmed by the detection of the active Caspase 3 and gasdermin E protein expressoion, as well as increased IL-1β and IL-18." (PMID 38077396, 2023). "XMD8-92 inhibited doxorubicin-induced activation of the NLRP3 inflammasome in H2373 mesothelioma cells as depicted by the absence of caspase-1 p20 and IL-1β in the medium after XMD8-92 treatment." (PMID 29416614, 2018). "Taken together, Vδ2 T cells can induce pyroptosis in mesothelioma cells via the canonical pathway but only induce active IL-18 and IL-1β in MSTO-luc but not H2052-luc cells, which may suggest the higher resistance of H2052-luc cells towards Vδ2 T cell killing." (PMID 38077396, 2023). "Further studies are in progress to offer an understanding of how asbestos-induced activation of the inflammasome and subsequent generation of biomolecules (IL-1β, IL-18, HMGB1 etc.)may lead to mesothelial cell transformation events and mesothelioma development." (PMID 24885895, 2014).
Peritoneal Fibrosis (11 papers, 2017 to 2025). Disorder characterized by a wide range of structural changes in PERITONEUM, resulting from fibrogenic or inflammatory processes. "It has been shown that high glucose-based PD solution activates NLRP3/IL-1β peritoneal mesothelial cells and that genetic deficiency of NLRP3 complex or IL-1β reduces inflammatory and peritoneal fibrosis model in mice." (PMID 35563220, 2022). "In the present study, we used mice deficient in NLRP3, ASC, and IL-1β, and generated MGO-induced peritoneal fibrosis, which is an excellent murine model for human PD-related peritoneal fibrosis." (PMID 31316105, 2019). "In the present study, we showed that deficiency of NLRP3, ASC, and IL-1β attenuates inflammatory and fibrotic responses after MGO treatment, resulting in less peritoneal fibrosis in a murine model of PD-related peritoneal fibrosis and EPS." (PMID 31316105, 2019). "We clearly showed that deficiency of NLRP3, ASC, or IL-1β reduced inflammatory and fibrotic responses in a MGO-induced peritoneal fibrosis model." (PMID 31316105, 2019). "MGO induced parietal and visceral peritoneal fibrosis in wild-type mice, which was significantly reduced in mice deficient in NLRP3, ASC, and interleukin-1β (IL-1β)." (PMID 31316105, 2019). "Since an abundant expression of inflammatory cytokines and chemokines is essential for the development and progression of peritoneal fibrosis, we further evaluated the effect of TA on the expression of some inflammatory cytokines and chemokines, including IL-6, IL-1β, TNF-α and MCP-1 by ELISA." (PMID 29179471, 2017). "Second, although MGO-induced peritoneal fibrosis was significantly attenuated in IL-1β-deficient mice, we could not detect substantial IL-1β production in response to MGO in cultured endothelial cells (data now shown)." (PMID 31316105, 2019). "LPS exposure in mouse peritoneum initiates the release of several inflammatory cytokines, including IL-1β, IL-6, and TNF-α, leading to further peritoneal fibrosis." (PMID 39728104, 2024). "The peritoneum can be damaged by various factors, activating macrophages and neutrophils that mediate NF-κB signalling pathways via Toll-like receptors (TLRs) and release numerous inflammatory cytokines, such as IL-6, IL-1β, IL-8, and TNF-α, leading to peritoneal fibrosis." (PMID 37817984, 2023). "Nintedanib attenuates the expression of cytokines/chemokines, including TNF-α, IL-1β, and IL-6, monocyte chemoattractant protein-1 (MCP-1) and prevents the macrophages infiltration to the injured peritoneum in chlorhexidine gluconate (CG)-induced peritoneal fibrosis." (PMID 35164664, 2022).
renal carcinoma (11 papers, 2018 to 2024). A carcinoma arising from the epithelium of the renal parenchyma or the renal pelvis. "Several studies have demonstrated the role of blocking IL-1β in promoting tumor regression in renal cancer, and our study provides new ideas about the possible mechanisms of this therapeutic approach." (PMID 39840068, 2024). "To characterize the genes regulated by IL1 in renal cancer cells, we performed RNA-sequencing of A498 cells either untreated or treated with interleukin-1β (IL1β; 30 ng/ml)." (PMID 35814450, 2022). "As control we investigated on the NLRP3 expression and production of IL-1β and IL-18 by cardiac cells and renal cancer cells during exposure to sunitinib alone or combined to resveratrol." (PMID 34178667, 2021). "All these results supported the conclusion that TEB cells promote renal cancer metastasis via inducing the IL-1β/HIF-2α/Notch1 signals." (PMID 32123166, 2020). "To address the effects of NFs on cytokines potentially involved in renal cancer progression, we examined, with ELISA assay, some relevant cytokines, such as IL6, VEGF, CXCL12, and IL1β, in medium with the presence or absence of NF-CM after 72 h." (PMID 31636361, 2020).
retinal detachment (11 papers, 2012 to 2024). An eye emergency condition which may lead to blindness if left untreated. "The probable mechanisms include integrin α5β1 stimulated NLRP3 inflammasome expression and mature IL-1β secretion, and then resulted in severe NV and significant leakage that caused total exudative retinal detachment." (PMID 29502235, 2018). "Since IL-1β production is an important contributor in early retinal detachment, we tested the anti-inflammatory capacity of simvastatin and amfenac also upon IL-1β exposure of RPE cells." (PMID 38530532, 2024). "IL-1α is an early marker of inflammation and cell injury, and patients with retinal detachment have increased IL-1β levels in the subretinal fluid." (PMID 38530532, 2024). "After retinal detachment, IL-1β blockade via subretinal injections of a neutralizing antibody decreased photoreceptor death in mice." (PMID 35251042, 2022). "MCP‐1 produced by Müller cells is a key mediator of photoreceptor apoptosis during retinal detachment, and IL‐1β is reported to promote the release of reactive oxygen species in the retinal pigment epithelium." (PMID 33207073, 2021). "Elevated IL-1β levels in the vitreous or retina lead to photoreceptor cell death in retinal detachment patients and in a mouse model, while reduced IL-1β levels inhibit photoreceptor cell death." (PMID 33122970, 2020). "In patients with retinal detachments, elevated levels of IL-1β have been detected in the vitreous or retina, indicating a role for IL-1β in disease pathogenesis." (PMID 31379825, 2019). "Most cytokines concentrations (IL-2, IL-6, IL-8, IL-10, IL-17, TNF-α, IFN-γ, VEGF) were not statistically significant different compared to the rhegmatogenous retinal detachment control group except IL-1β." (PMID 23049699, 2012). "In the retina and vitreous of patients with retinal detachments, higher IL-1β levels were reported." (PMID 35576057, 2022). "Furthermore, osmolarity-activated TRPV4 increases the production of IL-1β and IL-6 in intervertebral disc cells; during acute retinal detachment-induced swelling of Müller cells, TRPV4 activation led to MCP-1 release and photoreceptor death." (PMID 34789280, 2021). "Several studies claim that IL-1β is secreted by microglia after photo-oxidative damage, in neovascular age-related macular degeneration, in retinitis pigmentosa, and after retinal detachment." (PMID 31543759, 2019). "In support of this, a study involving a mouse retinal detachment model showed that photoreceptor cell death was reduced when IL-1β and CASP1 were inhibited, as well as in Nlrp3−/− mice with retinal detachment, also indicating a role for inflammasome activation in this disease." (PMID 31379825, 2019).
synovial sarcoma (11 papers, 2010 to 2025). "For example, both LL-37 and IL-17A were shown to induce the transcription of TNFα in human synovial sarcoma cells, and LL-37 with IL-1β was demonstrated to synergistically increase IL-8 production in airway epithelial cells." (PMID 40410820, 2025). "Here, we show that TRYP and TRYP-Ox significantly inhibited IL-1β–induced IL-6 secretion by SW982 synovial sarcoma cells and THP-1 monocytic cells, with TRYP-Ox being far more effective than TRYP." (PMID 32792961, 2020). "The expression of miR‐10a‐5p and TBX5 in the synovium of RA and human synovial sarcoma cell line SW982 stimulated by IL‐1β was determined by RT‐qPCR and Western blotting." (PMID 28782180, 2018). "This similar manner was shown in our previous report using a human synovial sarcoma cell line, SW982, which was induced by a combination of IL-1β and IL-17A." (PMID 33799537, 2021). "The expression levels of several key PRGs including CASP3, IL1B and DHX9 were significantly higher in the human synovial sarcoma cells SW-982 and hSS-005R, compared with those in the human skin fibroblast cell line (HSF)." (PMID 34925457, 2021). "Human synovial sarcoma cell line, SW982 cells stimulating with interleukin-1β (IL-1β) were transfected with miR-10a-5p mimic and siRNA of TBX5." (PMID 29545315, 2018). "For example, synthetic LXR agonists have been shown to inhibit IL-1β-induced production of Prostaglandin E2 (PGE2), as well as Cox-2 in osteoarthritic cartilage and in the synovial sarcoma cell line SW982." (PMID 21070649, 2010). "Numerous studies suggest that human SW982 synovial sarcoma cells share similar physiological and immunological properties with primary FLS and that IL-1β stimulation of SW982 cells can mimic the inflammatory status of synovial cells typically seen in RA patients." (PMID 32792961, 2020).
thyroid (11 papers, 2011 to 2026). "Specific cytokines appear to be associated with distinct irAEs; for instance, IL-17 has been linked to ICI-induced colitis, IL-1 and IL-6 to skin lesions, and IL-1β and IL-2 to thyroiditis." (PMID 40559409, 2025). "For instance, IL-17 is associated with colitis, IL-1 and IL-6 with skin lesions, and IL-1B, IL-2, and GM-CSF with thyroiditis." (PMID 39347217, 2024). "Baseline serum cytokine concentrations of IL-1β, IL-2, and GM-CSF were elevated in patients with thyroid related adverse reactions in a study of multiple solid tumors receiving immunotherapy." (PMID 36091125, 2022). "Both autocrine and paracrine production of IL-1β may happen in tumor microenvironment and malignant thyroid follicular cells are capable of recognize bacterial lipopolysaccharide and elicit IL-1β production." (PMID 32139737, 2020). "Importantly, mice that received IL-1β-exposed CD4+CD25+ T cells developed less severe thyroiditis as compared to control CD4+CD25+ T cell recipients." (PMID 21779356, 2011). "Serum IL-1β levels was under expressed in PTC group compared to healthy control group and other thyroid diseases." (PMID 32655554, 2020).
Tinnitus (11 papers, 2011 to 2025). Tinnitus is an auditory perception that can be described as the experience of sound, in the ear or in the head, in the absence of external acoustic stimulation. "The positive association between tinnitus scores and IL-1β levels in mice seems to confirm this." (PMID 35207270, 2022). "Finally, TNF-α and IL-1β gene expression in the IC and cochlea were both positively associated with tinnitus scores after four days of salicylate injections." (PMID 35207270, 2022). "Inflammatory markers such as TNF-α and IL-1β were found to be increased in tinnitus, and inflammatory cells such as microglia and astrocytes were found to be activated." (PMID 38719997, 2024). "The tinnitus scores of salicylate-treated mice showed significant positive associations with the expression levels of the TNF-a and IL-1b, and NR2B genes." (PMID 38027533, 2023). "It was established that TNF-α and IL-1β are increased in tinnitus, and that microglia and astrocytes are activated as well." (PMID 35207270, 2022). "So, besides increasing excitatory neurotransmission, TNF-α and IL-1β presumably also suppress inhibitory neurotransmission in tinnitus." (PMID 35207270, 2022). "Since IL-1β is hardly detectable in healthy brains, the elevation in its (gene) expression levels in rats with tinnitus suggests that IL-1β is present in tinnitus." (PMID 35207270, 2022). "Post-hoc analysis showed that, compared to the control group, the tinnitus group had significantly increased the IL-1β mRNA levels in the cochlea (3.5±1.1 versus 2.8±0.3, p = 0.031) and IC (2.9±0.5 versus 1.2±0.5, p<0.001)." (PMID 23533584, 2013). "Salicylate-induced tinnitus was associated with up-expression of NR2B, TNF-α, and IL-1β genes and with enzymatic inhibition of COX." (PMID 23533584, 2013). "The tinnitus scores of salicylate-treated mice showed significant positive associations with the expression levels of the TNF-α and IL-1β, and NR2B genes." (PMID 21477330, 2011). "Linear regression analysis revealed a significant positive association between tinnitus scores and expression levels of TNF-α, IL-1β, and NR2B genes in cochlea and IC." (PMID 21477330, 2011). "Linear regression analysis showed that tinnitus scores were positively associated with gene expression level of NR2B and with gene expression levels of TNF-α and IL-1β in cochlea and IC." (PMID 21477330, 2011). "Interestingly, IL-10 levels increased with the chronicization of tinnitus, while levels of IL-1α, IL-1β, IL-2, IFN-γ, TNF-α, and Transforming Growth Factor (TGF)-β remained unchanged." (PMID 40697272, 2025). "Interestingly, this increase was consistently coexistent with increases in TNF-α and IL-1β in animals with tinnitus throughout the entire auditory pathway." (PMID 35207270, 2022). "IL-1β (gene) expression was consistently increased in experimental tinnitus." (PMID 35207270, 2022). "Given the role of TNF-α, IL-1β and microglia in the tinnitus pathophysiology, these mediators could potentially be a target for treatment." (PMID 35207270, 2022). "Recently, our study group found that mRNA expression levels of the NR subtype 2B (NR2B) gene, tumor necrosis factor –α (TNF-α) and interleukine-1β (IL-1β) genes were elevated significantly in the cochlea and in the inferior colliculus (IC) in salicylate-induced tinnitus." (PMID 23533584, 2013). "We conclude that salicylate treatment resulting in tinnitus augments expression of the TNF-α and IL-1β genes in cochlea and IC of mice, and we suggest that these proinflammatory cytokines might lead to tinnitus directly or via modulating the NMDA receptor." (PMID 21477330, 2011). "In addition, the tinnitus scores showed significant positive associations with the gene expression levels of TNF-α, IL-1β, and NR2B in both cochlea and IC." (PMID 21477330, 2011).
Tinnitus (continued). "However, IL-1β protein levels in the IC were significantly decreased in the Spirulina group (0.91±0.07 versus 1.45±0.18, p = 0.001) and in the C-PC group (0.56±0.01 versus 1.45±0.18, p<0.001), compared with the tinnitus group." (PMID 23533584, 2013). "Therefore, it is also reasonable to hypothesize that TNF-α and IL-1β might contribute to tinnitus via augmenting NMDA receptor expression and/or its functions." (PMID 21477330, 2011). "There is accumulating evidence that tinnitus is associated with neuroinflammation, such as a positive correlation between the circulating cytokines IL-1β and TNF-α with psychometric scores of tinnitus." (PMID 37048724, 2023). "Experimental studies found an increase of TNF-α in the cochlea, the CN, the IC, and the AC, as well as an increase of IL-1β in the cochlea, the IC, the MGB, and the AC of animals with tinnitus." (PMID 35207270, 2022). "However, it is not clear whether the increased (gene) expression of IL-1β (partly) caused tinnitus or vice versa." (PMID 35207270, 2022). "The first network included tinnitus loudness (SL) and correlated blood parameters (TNF-α, IL-1b, IGF-1) and their covariates (age, hearing threshold, systolic blood pressure, LDL cholesterol, VEGF, non-classical monocytes, intermediate monocytes)." (PMID 35814090, 2022). "CPC and S. platensis water extract reduced salicylate-induced tinnitus and down-regulated mRNA and protein expression for NR2B, TNF-α, IL-1β, and COX-2 genes in the cochlea and IC of SAMP8 mice." (PMID 27590453, 2016). "On the other hand, dietary supplementation with C-PC or Spirulina platensis water extract significantly reduced the salicylate-induced tinnitus and down-regulated the mRNAs expression of NR2B, TNF-α, IL-1β mRNAs, and COX-2 genes in the cochlea and IC of mice." (PMID 23533584, 2013). "We evaluated tinnitus and mRNA expression levels of TNF-α, IL-1β, and N-methyl D-aspartate receptor subunit 2B (NR2B) genes in cochlea and inferior colliculus (IC) of mice after intraperitoneal injections of salicylate." (PMID 21477330, 2011). "While we observed correlations of IL-1b, TNF-α, and IGF-1 with tinnitus loudness, these associations did not persist in network analysis." (PMID 35814090, 2022). "The expression levels of NR2B, tumor necrosis factor-α (TNF-α) and interleukine-1β (IL-1β) genes increased significantly, whereas cyclooxygenase type 2 (COX-2) gene expression decreased in the cochlea and IC of mice with salicylate-induced tinnitus." (PMID 27590453, 2016). "In this study, we aim to investigated whether C-PC or spirulina platensis water extract could reduce the tinnitus score and expression levels of NR2B, TNF-α, IL-1β, and COX-2 genes in the cochlea and IC in response to intraperitoneal injections of salicylate." (PMID 23533584, 2013). "Post-hoc analysis showed that, compared to the control group, the tinnitus group had not significantly increased IL-1β protein levels in the IC (1.45±0.18 versus 1.16±0.08, p = 0.057)." (PMID 23533584, 2013). "Therefore, we suggested that the beneficial effects of spirulina or C-PC on tinnitus mainly via inhibiting mRNA expression of NR2B, TNF-α, IL-1β, and/or COX-2 genes." (PMID 23533584, 2013). "This experimental study showed that the both of spirulina platensis water extract and its active component (C-PC) could reduce salicylate-induced tinnitus and reduce expression of NR2B, TNF-α, IL-1β, and COX-2 genes in the cochlea and IC." (PMID 23533584, 2013). "Changes in the gene expressions for tumor necrosis factor-α (TNF-α) and/or interleukin-1β (IL-1β) during tinnitus have not been previously reported." (PMID 21477330, 2011). "For instance, IL-1β was found in 30 patients with chronic tinnitus to correlate with distress levels, as well as tinnitus awareness, and IL-10 was found lower in subjects with tinnitus when compared to those without tinnitus (n = 114)." (PMID 38079022, 2023).